HK2 (hexokinase 2)
Description:
Catalyzes the phosphorylation of hexose, such as D-glucose and D-fructose, to hexose 6-phosphate (D-glucose 6-phosphate and D-fructose 6-phosphate, respectively). Mediates the initial step of glycolysis by catalyzing phosphorylation of D-glucose to D-glucose 6-phosphate. Plays a key role in maintaining the integrity of the outer mitochondrial membrane by preventing the release of apoptogenic molecules from the intermembrane space and subsequent apoptosis.
Synonyms: HKII; HXK2
Tractability: Small molecule: a structure with a bound ligand is known; a high-quality ligand is known; it has a high-quality binding pocket. Antibody: UniProt places it where antibodies can reach, with high confidence. PROTAC: ubiquitination databases record sites on it; its protein half-life has been measured; a small molecule that binds it is known.
Target class: Enzyme
Gene: Protein-coding gene on chromosome 2 (74,834,079 to 74,893,359, forward strand). Ensembl gene ENSG00000159399.
Subcellular location: Mitochondrion outer membrane; Cytoplasm, cytosol
Subcellular location (Human Protein Atlas): Cytosol; Mitochondria; Centrosome; Vesicles
Pathways (Reactome):
Metabolism: Glycolysis
Gene Ontology:
Molecular function: glucokinase activity; hexokinase activity; protein binding; fructokinase activity; ATP binding; D-glucose binding
Biological process: apoptotic mitochondrial changes; canonical glycolysis; glucose 6-phosphate metabolic process; maintenance of protein location in mitochondrion; positive regulation of angiogenesis; positive regulation of type 2 mitophagy; protein localization to mitochondrion; fructose 6-phosphate metabolic process; glucose metabolic process; glycolytic process; carbohydrate derivative metabolic process; carbohydrate metabolic process; hexose metabolic process; intracellular glucose homeostasis; organophosphate metabolic process
Cellular component: cytosol; membrane; mitochondrial outer membrane; mitochondrion
Genetic constraint (gnomAD): Loss-of-function variants: 39 observed, 88.99 expected, observed/expected ratio (o/e) 0.44, 90% interval 0.34 to 0.57. The upper end of that interval is the gene's LOEUF score, 0.57, which puts it in group 2 of 6, group 1 being the genes least tolerant of losing a copy. Missense variants: 965 observed, 1,259.4 expected, observed/expected ratio (o/e) 0.77, 90% interval 0.73 to 0.81. Synonymous variants: 420 observed, 469.98 expected, observed/expected ratio (o/e) 0.89, 90% interval 0.82 to 0.97.
Homologues: Orthologues: chimpanzee HK2 (99% identical), macaque HK2 (99% identical), pig HK2 (96% identical), dog HK2 (96% identical), tropical clawed frog hkdc1 (85% identical), zebrafish hk2 (79% identical), mouse Hk2 (49% identical), rat Hk2 (49% identical). Paralogues in human: HK1 (73% identical), HKDC1 (68% identical), HK3 (56% identical), GCK (28% identical).
Diseases named in the same sentence as HK2 in open-access papers:
HK2 is named in the same sentence as 329 diseases in open-access papers, as found by Europe PMC text mining. Sharing a sentence is not in itself a finding about the gene and the disease. The quoted sentences say what the papers report.
breast cancer (218 papers, 2000 to 2026). A primary or metastatic malignant neoplasm involving the breast. "In mouse models of breast cancer metastasis, HK2 deficiency decreases SNAIL protein levels and inhibits SNAIL-mediated epithelial mesenchymal transition and metastasis." (PMID 40443971, 2025). "The decrease in glycolysis observed in genistein-treated tamoxifen-resistant (TAM-R) breast cancer cells is likely linked to important changes in HK2 and STAT3 expression." (PMID 39859445, 2025). "In breast cancer, the upregulation of miR-200c was associated with the inhibition of lactate production and reduced HK2 protein levels." (PMID 38408962, 2024). "In breast cancer cells, HK2 is highly expressed and is associated with the occurrence and progression of breast cancer." (PMID 37377974, 2023). "To define the mechanism underlying HK2-upregulated PD-L1 expression in breast cancer cells, we performed co-immunoprecipitation analyses and showed that endogenous HK2 interacted with endogenous IκBα in MCF-7 and BT-549 cells." (PMID 37377974, 2023). "An increase in HK2 transcription by the yes-associated protein (YAP) axis also promotes the migration of breast cancer cells." (PMID 34552932, 2021). "High HK2 expression in lung, ovarian, pancreatic, breast cancers and hepatocellular carcinoma was shown to be associated with poor patient prognosis." (PMID 28105937, 2016). "Furthermore, breast cancer reprograms energy metabolism in tumour-associated adipose tissue, increasing HK2 expression in malignant tumours compared to benign tumours." (PMID 41007296, 2025). "Emerging evidence indicates that HK2 deficiency attenuates breast cancer metastasis." (PMID 40756987, 2025). "Finally, in mouse models of breast cancer metastasis, HK2 deficiency decreases SNAIL protein levels and inhibits SNAIL-mediated epithelial mesenchymal transition and metastasis." (PMID 35173161, 2022). "Notably, investigations showed that upregulation of glucose metabolism, especially HK2 expression, was associated with the chemoresistance phenotypes of breast cancer cells." (PMID 34378321, 2021). "LDHA is associated with breast cancer resistance to paclitaxel/trastuzumab and myeloma relapse; overexpression of hexokinase 2 (HK2) is involved in cisplatin resistance in ovarian cancer cells, by enhancing autophagy and the increased expression of PDK2 is linked to paclitaxel resistance in NSCLC." (PMID 30873026, 2019). "Furthermore, HK2 is a key enzyme associated with glycolysis in cancers, including breast cancer." (PMID 31488193, 2019). "Given that the only substrate yet identified for hK2 activity is the precursor of prostate-specific antigen (PSA), the expression of which in breast carcinomas may be associated with favourable prognosis, our purpose was to examine the expression pattern of both hK2 and PSA in breast tumour tissues." (PMID 10646889, 2000). "In particular, hsa-let-7b-5p has been shown to inhibit aerobic glycolysis and metastasis in breast cancer by repressing hexokinase 2, indicating its central role in metabolic reprogramming and tumor suppression (PMID: 37019900)." (PMID 41268575, 2025). "We have observed the localization of PFKL to lamellipodia of migrating breast cancer cells, where it colocalized with hexokinase-2 and pyruvate kinase M2." (PMID 41159217, 2025). "For instance, in hepatocellular carcinoma models, PKA activation diminishes HK2 expression, indicating a potential regulatory circuit that mediates the action of 2-DG in breast cancer." (PMID 41415273, 2025). "(2019) demonstrated the therapeutic effect of targeting the ROS/PI3K/AKT/HIF‐1α/HK2 axis in breast cancer." (PMID 40415238, 2025). "In estrogen receptor (ER)-positive breast cancer cells, HK2 suppresses mTOR activity through an interaction with mTOR, which promotes autophagy and chemoresistance to tamoxifen." (PMID 40612109, 2025). "Both PKM2 and HK2 were significantly upregulated in breast cancer tissues compared to adjacent normal tissues." (PMID 41154605, 2025).
breast cancer (continued). "HK2 knockout can inhibit tumorigenesis in mouse models of KRAS-driven lung cancer, ErbB2-driven breast cancer, and PTEN-deficient PC." (PMID 39770959, 2024). "In breast cancer cells, through the mTOR pathway by specifically targeting HK2, miR-216b promotes autophagy and apoptosis." (PMID 39224810, 2024). "For instance, physciosporin, a potent anticancer lichen compound, downregulates HK2 mRNA expression and inhibits breast cancer cell proliferation." (PMID 39765841, 2024). "In a previous study, breast cancer cells induced overexpression of 5′-adenosine monophosphate-activated protein kinase (AMPK) and hexokinase 2 (HK2) in cancer-associated adipocytes located in the peritumoral AT." (PMID 39338206, 2024). "It has been demonstrated that in breast cancer Hexokinase II (HK2), the rate-limiting enzyme in the glycolytic pathway promotes cancer progression." (PMID 39201646, 2024). "Researchers have successfully targeted and eliminated breast cancer stem cells by blocking important enzymes in the glycolytic pathway, including hexokinase 2 (HK2), phosphofructokinase (PFK), and lactate dehydrogenase A (LDHA)." (PMID 38891090, 2024). "Depletion of HK2 abolished the initiation and progression of lung cancer and breast cancer both in vitro and in vivo." (PMID 38339062, 2024). "Modulating HK2 activity alters a cancer cell’s glycolytic rate, progression, and paclitaxel resistance in breast cancer cells." (PMID 39408832, 2024). "For example, let‐7b‐5p inhibits breast cancer cell growth and metastasis by suppressing HK2‐mediated aerobic glycolysis." (PMID 38886335, 2024). "All these results showed that CMA promoted breast cancer angiogenesis through regulation of HK2-mediated aerobic glycolysis." (PMID 36913368, 2023). "The expression of HK2, which can be induced by erbB2/Neu, was significantly increased in breast cancer specimens compared to normal tissue." (PMID 37377974, 2023). "Under high glucose conditions, HK2 acts as a protein kinase and phosphorylates IκBα at T291 in breast cancer cells, leading to the rapid degradation of IκBα and activation of NF-κB, which enters the nucleus and promotes PD-L1 expression." (PMID 37377974, 2023). "Then Western blotting further showed that LAMP2A knockdown led to decreased protein level of HK2 in breast cancer cells, while LAMP2A overexpression promoted the HK2 protein level in breast cancer cells." (PMID 36913368, 2023). "Further, HK2 is associated with the recurrence and poor prognosis of breast cancer (BC)." (PMID 36768924, 2023). "We demonstrated that HK2 plays a key role in regulating PD-L1 in breast cancer cells in response to high glucose." (PMID 37377974, 2023). "Metabolic enzymes, being related to glucose transmembrane transport and glycolysis such as glucose transporter 1 (GLUT1) and hexokinase 2 (HK2) are highly expressed in breast cancer cells." (PMID 37120513, 2023). "It has been shown that HK2 is required for tumorigenesis in an ErbB2/ Her2‐driven breast cancer mouse model, and HK2 ablation inhibits the malignant phenotype of breast cancer cells in vitro and in vivo." (PMID 36807772, 2023). "Since lactate is the final product of glycolysis, and HK2 was a key mediator in glycolysis pathway, we then determined HK2 levels in breast cancer cells." (PMID 36913368, 2023). "Hsa_circ_0069094 is upregulated in breast cancer and regulates HK2 expression by interacting with miR-591." (PMID 37204526, 2023). "Since HK2 is a key enzyme of aerobic glycolysis and performs a vital function in breast cancer, we screened potential miRNAs targeting HK2 using miRDB, TargetScan, and StarBase databases." (PMID 37019900, 2023). "A recent investigation identified that increased expression of HK2 correlates with the metastatic ability of breast cancer." (PMID 36984785, 2023). "Among them, circRNF20 binds to miR-487a and promotes the expression of HIF-1α, thereby upregulating HK2 levels and accelerating the Warburg effect in breast cancer cells." (PMID 37204526, 2023).
breast cancer (continued). "It has been confirmed that HK2 content is increased in the resected tissues of the lung, gastrointestinal, and breast malignant tumors." (PMID 37580808, 2023). "In breast cancer cells, overexpression of HK2 promotes tumor glycolysis and metastasis, leading to poor prognosis." (PMID 37204526, 2023). "In mouse models, HK2 has been shown to be essential for initiation and continued maintenance of K-Ras–driven lung cancer and ErbB2-driven breast cancer." (PMID 37343102, 2023). "Accordingly, these data strongly support that the let-7b-5p/HK2 axis plays critical pathological roles in breast cancer." (PMID 37019900, 2023). "In recent years, many studies have shown that HK2 is highly expressed in breast cancer, liver cancer, glioma, and esophageal cancer and can promote tumor progression through energy metabolism and anti-apoptotic signaling pathways." (PMID 37854321, 2023). "In mouse models of KRAS-driven lung cancer and HER2-driven breast cancer, HK2 was necessary for tumor initiation and maintenance as demonstrated using Hk2 conditional knockout mice." (PMID 37190033, 2023). "Resibufogenin regulates the miR-143-3p/HK2 axis to inhibit tumor growth and glycolysis in breast cancer." (PMID 37019900, 2023). "CircKLHL24 can inhibit the proliferation and migration of breast cancer cells, downregulate the levels of HK2, GLUT1 and LDHA, and upregulate the expression of ALX4 by competitively binding miR-1204, thereby achieving tumor inhibition." (PMID 37204526, 2023). "MiR-216b potentiates breast cancer cell autophagy and apoptosis in vitro by targeting HK2 through the mTOR signaling pathway." (PMID 37019900, 2023). "In patients with breast cancer, let-7b-5p expression is significantly downregulated and is negatively correlated with HK2 expression." (PMID 37019900, 2023). "The present study provides a new link between CMA and angiogenesis, we show that CMA promotes VEGFA expression via regulation of HK2-mediated aerobic glycolysis, thus enhancing breast cancer angiogenesis." (PMID 36913368, 2023). "HIF-1α has been positively correlated with HK2 expression in breast cancer tissues, and bioinformatics analysis has shown that HIF-1α has a hypoxic response element (HRE) in the upstream promoter region of HK2." (PMID 36793034, 2023). "We showed here that HK2, acting as a protein kinase, phosphorylates IκBα at T291 in breast cancer cells, leading to IκBα degradation and subsequent activation of NF-κB for upregulation of PD-L1 transcription." (PMID 37377974, 2023). "The Correlation between HK2 Expression and Clinicopathological Characteristics in Breast Cancer Patients (n=220 cases)." (PMID 37377974, 2023). "HK2 phosphorylates IκBα at T291, resulting in IκBα rapid degradation and NF-κB activation, resulting in enhanced PD-L1 transcription and breast cancer cell immune evasion." (PMID 37377974, 2023). "On the other hand, it emerged that HK2 can directly bind to miR-143 besides miR-155 and modulate the glycolysis of breast cancer." (PMID 36230935, 2022). "hsa_circ_0069094 was found to upregulate HK2 expression by binding to miR-591, thus promoting cellular malignancies and glycolysis in breast cancer." (PMID 35223093, 2022). "Some studies have shown that HIF-1/HK2 can synergistically promote the development of breast cancer." (PMID 36713522, 2022). "HK2, PKM2, and LDHA, glycolysis-associated proteins, affect tumorigenesis, cell growth, migration, autophagy of breast cancer." (PMID 34951340, 2022). "To further explore the relationship between HK2 and autophagy, we performed bioinformatics analysis comparing between the high and low HK2 expression groups in breast cancer patients." (PMID 36186902, 2022). "For breast cancer, the expression of HK2 total protein was higher in tumor tissue than in normal tissue." (PMID 36335239, 2022). "Overall, the knockdown of CircRNF20 seems to be an efficient way to reduce miR-487a/HIF-1α/HK2-mediated glycolysis and the proliferation of breast cancer cells." (PMID 36230935, 2022).
breast cancer (continued). "Another member of the Snail family, Slug, has been shown to protect tamoxifen−resistant breast cancer cells via the slug/hexokinase 2 signaling pathway." (PMID 36232636, 2022). "Consistently we found that the depletion of HK2 in mouse models of breast cancer metastasis inhibited metastasis via decreased SNAIL protein level and its effect on EMT." (PMID 35173161, 2022). "Increased mitochondrial substrate shuttle flux (G-3-P[18O]), and overexpression of HK2 suggest a tight relationship between the glycolytic phosphotransfer network and mitochondria in breast cancer cells." (PMID 35712500, 2022). "Among molecular subtypes of breast cancer, luminal B subtype patients showed a significant increase in HK2 and PKM2 expression, whereas most samples with upregulated PFKM fell into the luminal A subtype." (PMID 35328104, 2022). "When HK2 is downregulated in breast cancer cells, lactate secretion and glycolysis baseline are significantly reduced." (PMID 36059650, 2022). "Our study reveals unprecedented evidence of a role for histone H2AX in promoting metastatic ability of invasive breast cancer cells, potentially via transcriptional regulation of hexokinase-2 and glycolysis maintenance." (PMID 35260660, 2022). "Our findings reveal a role for histone H2AX in controlling the metastatic ability of breast cancer cells via maintenance of HK2-driven glycolysis." (PMID 35260660, 2022). "Chemotherapy resistance can also be induced by upregulating HK2 expression, which is an enzyme of crucial importance that is involved in resistance to breast cancer and its prognosis through tumor glycolysis." (PMID 36059650, 2022). "The degradation of HIF-1α accelerates the reversal of the expression of glycolysis-related proteins GLUT1, PDK1, and HK2 in cancer cells, which weakens the glycolysis of breast cancer cells and indirectly leads to tumor growth inhibition." (PMID 35350760, 2022). "HK2 knockdown inhibits the proliferation of MDA-MB-231 breast cancer cells and enhances the ability of 5-FU to kill them." (PMID 36059650, 2022). "A study managed by Ni and colleagues revealed another phenomenon of chemoresistance in which circHIKP3 overexpression suppressed miR-1286 to enhance hexokinase 2 (HK2) expression and decreased the response to paclitaxel treatment in breast cancer cells." (PMID 36292157, 2022). "Here, we also showed that systemic deletion of HK2, which emulates drug therapy, inhibited breast cancer metastasis in a mouse model of breast cancer metastasis." (PMID 35173161, 2022). "The current study was designed to assess the expression level of three key glycolytic genes, HK2, PFKM, and PKM2, along with their association with clinicopathological parameters and molecular subtypes in breast cancer cohort of Pakistan." (PMID 35328104, 2022). "One study reports that curcumin increases sensitivity to TAM in breast cancer cells by regulating the HK2 pathway." (PMID 36059650, 2022). "The results of the CPTAC datasets showed higher expression of HK2 total protein in the primary tissue of breast cancer, KIRC, colon cancer, LUAD (Lung adenocarcinoma), ovarian cancer and UCEC (p < 0.001) than in normal tissues." (PMID 36335239, 2022). "As a glycolysis inhibitor, miR-143 inhibited glycolysis in breast cancer cells by downregulating the expression of HK2, which is a pivotal regulator of aerobic glycolysis and tumor growth, and the systemic delivery of miR-143 agomir inhibited tumor growth." (PMID 36050724, 2022). "LncRNA BCAR4 coordinated the Hedgehog signaling pathway to enhance the transcription of glycolysis activators HK2, facilitating tumorigenesis in breast cancer." (PMID 36072431, 2022). "This observed HK2 dysregulation in breast cancer patients is more evident in breast cancer in HIV-infected women, which indicates the retroviral interactions between HK2 and HIV in the upregulation of HK2 in these tumors." (PMID 34778024, 2021).